ATP5ME (ATP synthase membrane subunit e)
Description:
Subunit e, of the mitochondrial membrane ATP synthase complex (F(1)F(0) ATP synthase or Complex V) that produces ATP from ADP in the presence of a proton gradient across the membrane which is generated by electron transport complexes of the respiratory chain. ATP synthase complex consist of a soluble F(1) head domain - the catalytic core - and a membrane F(1) domain - the membrane proton channel. These two domains are linked by a central stalk rotating inside the F(1) region and a stationary peripheral stalk. During catalysis, ATP synthesis in the catalytic domain of F(1) is coupled via a rotary mechanism of the central stalk subunits to proton translocation (Probable). In vivo, can only synthesize ATP although its ATP hydrolase activity can be activated artificially in vitro (By similarity). Part of the complex F(0) domain.
Synonyms: ATP5I; ATP5K
Tractability: Small molecule: a structure with a bound ligand is known. PROTAC: ubiquitination databases record sites on it.
Gene: Protein-coding gene on chromosome 4 (672,423 to 674,369, reverse strand). Ensembl gene ENSG00000169020.
Subcellular location: Mitochondrion; Mitochondrion inner membrane
Subcellular location (Human Protein Atlas): Mitochondria
Pathways (Reactome):
Metabolism: Formation of ATP by chemiosmotic coupling
Organelle biogenesis and maintenance: Cristae formation
Gene Ontology:
Molecular function: protein binding; proton-transporting ATP synthase activity, rotational mechanism; protein-containing complex binding; proton transmembrane transporter activity
Biological process: proton motive force-driven mitochondrial ATP synthesis; proton motive force-driven ATP synthesis; proton transmembrane transport
Cellular component: mitochondrion; proton-transporting ATP synthase complex; mitochondrial inner membrane; membrane
Genetic constraint (gnomAD): Loss-of-function variants: 10 observed, 10.39 expected, observed/expected ratio (o/e) 0.96, 90% interval 0.59 to 1.61. The upper end of that interval is the gene's LOEUF score, 1.61, which puts it in group 6 of 6, group 1 being the genes least tolerant of losing a copy. Missense variants: 115 observed, 85.84 expected, observed/expected ratio (o/e) 1.34, 90% interval 1.15 to 1.56. Synonymous variants: 45 observed, 32.52 expected, observed/expected ratio (o/e) 1.38, 90% interval 1.09 to 1.76.
Homologues: Orthologues: chimpanzee ATP5ME (100% identical), pig ATP5ME (96% identical), macaque ATP5ME (94% identical), guinea pig Atp5me (87% identical), mouse Atp5me (87% identical), rat Atp5me (86% identical), dog ATP5ME (70% identical), zebrafish atp5meb (67% identical), tropical clawed frog atp5me (65% identical), zebrafish atp5mea (64% identical), Caenorhabditis elegans R04F11.2 (35% identical).
Diseases named in the same sentence as ATP5ME in open-access papers:
ATP5ME is named in the same sentence as 17 diseases in open-access papers, as found by Europe PMC text mining. Sharing a sentence is not in itself a finding about the gene and the disease. The quoted sentences say what the papers report.
epilepsy (1 paper, 2023). A brain disorder characterized by episodes of abnormally increased neuronal discharge resulting in transient episodes of sensory or motor neurological dysfunction, or psychic dysfunction. "ATP5ME and NDUFA1 showed higher expression in blood RNA of the TSC epilepsy group compared with the other two groups, and encode mitochondrial components important for mitochondrial energy production." (PMID 37996417, 2023).
tumor (2 papers, 2020 to 2022). "In addition, we found that many genes associated with ATP synthesis, such as ATP5F1D, ATP5ME, and ATP5MF, and genes associated with NADH oxidation, such as NDUFS8, NDUFB10, and NDUFC1, were overexpressed in LIHC and LUAD tumor tissues." (PMID 33262783, 2020).
ATP5ME also shares sentences with these, for which no sentence is quoted: Alzheimer disease (1 paper); atherosclerosis (1); breast carcinoma (1); cancer (1); colorectal cancer (1); COVID-19 (1); Hepatic fibrosis (1); infection (1); leukemia (1); multiple sclerosis (1); myocarditis (1); pancreatic cancer (1); preeclampsia (1); schizoaffective disorder (1); schizophrenia (1).